TNF (tumor necrosis factor)
Diseases named in the same sentence as TNF in open-access papers (continued):
Sharing a sentence is not in itself a finding about the gene and the disease.
Granuloma (continued). "As assayed by the TUNEL method, infection of Mtb resulted in apoptosis of human PBMCs, however treatment of granulomas with anti-TNFα mAb, did not result in any change in the number of apoptotic cells when compared with granulomas treated with control IgG." (PMID 23308269, 2013). "All double deficient mice exhibited strong late TNF-α hyper-responses to the respective TLR ligands and developed splenomegaly and intrahepatic granulomas with a delay (not shown)." (PMID 22745710, 2012). "However, different cytokines including IL-4, TNF-α, IL-10, and IFN-γ are produced during the course of granuloma formation." (PMID 22013486, 2012). "The status of the host protective factors TNF α, IFN γ and iNOS activity increased with the concomitant decrease in IL 10 and TGF β level in imipramine treated infected hamsters and evolution of matured sterile hepatic granuloma." (PMID 23301108, 2012). "For example, tumor necrosis factor-α (TNF-α) enhances the activity of macrophage to kill replicating Mtb in synergy with interferon-γ (IFN-γ) and contributes to the formation of granuloma and prevention of mycobacterial dissemination through decreased cell migration." (PMID 21447195, 2011). "Their results showed that IL-4 positive granulomas tended to be non-necrotic whereas all necrotic granulomas were TNF-α positive and negative or weakly positive for IL-4 and IFN-γ." (PMID 19156215, 2009). "Granulomas dissolve in the absence of TNF-α, allowing re-growth and spread of mycobacteria." (PMID 39854270, 2025). "This spatial model accounted for granulomas as evolving regions over time and incorporated variables such as the density of macrophages, Treg, Th1, and Th17 cells, as well as concentrations of IL-2, IL-10, IL-12, IL-13, IFN-γ, TNF-α, TGF-β, GM-CSF, and CCL20, along with fluid velocity." (PMID 39996765, 2025). "considers the progression of sarcoidosis in terms of a granuloma radius represented as a conglomerate of Mφ, Th1, Treg and Th17 cells, which affect each other through a network of cytokines and chemokines (IL-2, IL-10, IL-12, IL-13, chemokine ligand 20, IFN-γ, TNF-α and TGF-β)." (PMID 38550585, 2024). "In Silirum® induced granulomas, a higher number of MHC-II and TNF-expressing cells and a lower number of M2 macrophages suggested an improved antigen presentation, which could be due to the better antigen distribution and reduced tissue damage induced by this vaccine." (PMID 38352038, 2024). "In addition, negative brown immunostaining for TNF protein was observed in all organs of well-developed granulomas." (PMID 36670836, 2023). "Of particular interest was the observation that the innate granulomas (both uninfected [UIG] and BCG-infected [IIG]) did not produce high levels of cytokines like TNF-α, IFN-γ, and IL-2 associated with T cell production and release, further supporting the previous statement." (PMID 34287004, 2021). "However, LBR5, LBR6 and LBR8 induced increased levels of pro-inflammatory cytokines (IFN-γ, IL-2, IL-6, TNF-α and IL-17A), which are consistent with a robust Th1 immune response that especially promotes cellular proliferation and the formation of granulomas (IFN-γ and TNF-α)." (PMID 34046037, 2021). "The time of diagnosis, the age range of the patients included, the use of anti-TNF by almost one-third of the patients, and the conventional histopathological analysis may have influenced the lack of detection of granulomas in our sample." (PMID 34203639, 2021). "Spatial studies of human tuberculous granulomas find that necrotic tuberculous granulomas are enriched for LTA4H and TNF as compared to nonnecrotic granulomas from the same lung, making it plausible that corticosteroids exert their effects through these determinants." (PMID 33658385, 2021). "However, subsequent work from this group found that TNF knockout mice did not have a defect in granuloma formation." (PMID 33465071, 2021).
Granuloma (continued). "However, we recently reported that anti-TNF antibodies do not affect the formation of granulomas but that of MGCs." (PMID 32411623, 2020). "Moreover, adalimumab, a human monoclonal anti-TNF-α IgG1 inhibited MGC formation in granuloma, without altering IL-10 secretion and induced macrophage apoptosis." (PMID 31475008, 2019). "After the blockade of TNF-α by Infliximab, we sought to check for differences between the groups, and whether this blockade influenced or not the formation of the granuloma." (PMID 29543912, 2018). "However, TNF adding to PBMCs from septic patients unable to form granulomas did not restore the formation of immune and innate granulomas." (PMID 27441846, 2016). "Similarly, TNF did not increase the percentage of innate granulomas in patients unable to form granulomas (20 ± 25%, 27 ± 38%; 28 ± 42% at days 3, 6 and 9, respectively)." (PMID 27441846, 2016). "Similarly, adding anti-TNF mAb to control PBMCs did not inhibit the formation of immune and innate granulomas." (PMID 27441846, 2016). "The release of TNF (182 and 232 pg/ml, respectively) by PBMCs from the patients who formed immune (BCG) and innate (CB) granulomas was significantly (p < 0.05) higher than that of PBMCs from patients unable to form immune and innate granulomas (36 and 38 pg/ml, respectively)." (PMID 27441846, 2016). "Similarly, anti-TNF mAb did not affect the percentage of innate granulomas (48 ± 42%, 78 ± 32% and 88 ± 21% at days 3, 6 and 9, respectively)." (PMID 27441846, 2016). "TNF-α protein has been detected in skin lesions across the leprosy spectrum with greater production of TNF-α in lesions from tuberculoid leprosy (TT) patients in whom granuloma formation is better and few or no mycobacteria are detectable." (PMID 22180790, 2011). "There is no published evidence about whether granulomas on chest radiography in patients living in histoplasmosis endemic areas are predictive of development of histoplasmosis in patients on TNF-inhibitors." (PMID 21605439, 2011). "In the absence of TNF there was no formation of well-defined granulomas." (PMID 16285886, 2005). "Although TNF-KO mice could not contain the infection, reconstituted TNF-KO mice developed granuloma (data not shown) and were able to control acute infection and bacterial growth in the lungs." (PMID 16285886, 2005). "Bacterial burdens did not correlate with expression of IFN-γ, TNF-α, TGF-β, granuloma stage, or lung lesion score, although there was a modest positive correlation with IL-10 expression." (PMID 34026898, 2021). "Treatment of granulomas from BCG-vaccinated subjects with lower concentrations of PZA and INH in the presence or absence of L-GSH led to higher TNF-α production." (PMID 31569759, 2019). "In spite of microscopic morphological similarities, significant differences were seen between late stage granulomas of the lung compared to those of the tracheobronchial lymph nodes for IL-17A, IFN-γ, TGF-β, IL10 and IL-22 but not for TNF-α." (PMID 27902779, 2016). "Additionally, significant differences were noted between granulomas from two different thoracic lymph nodes that both receive afferent lymphatics from the lungs (i.e., tracheobronchial and caudal mediastinal lymph nodes) for TNF-α, IL-17A, IFN-γ, TGF-β and IL-10 but not for IL-22." (PMID 27902779, 2016). "Granulomas were characterised as necrotic or non-necrotic, graded histologically and investigated for the mRNA expression of IL-12, IFN-γ, TNF-α and IL-4 by in situ hybridisation." (PMID 19156215, 2009). "In this case, the absence of granulomas does not rule out the diagnosis of MCD if other characteristic features are present, and the use of anti-TNF therapy (adalimumab) could have suppressed granuloma formation." (PMID 40614548, 2025).
injury (341 papers, 1997 to 2026). Damage inflicted on the body as the direct or indirect result of an external force, with or without disruption of structural continuity. "The damaged liver releases HMGB1, which binds to its receptors, and this subsequently activates signaling pathways, leading to the secretion of proinflammatory cytokines including TNF-α, which causes acute liver injury." (PMID 37511276, 2023). "BLM-induced acute lung injury was associated with a significant increase in the mean concentration of TNF-α, IL-6, IL-1B, and NF-kB in lung tissues compared to that in the control (p < 0.05)." (PMID 36500388, 2022). "Among the pro-inflammatory cytokines that trigger the CisPT-mediated pathophysiological developments associated with brain injury; TNF-α and IL-6 are extremely potent as they also stimulate the discharge of other cytokines as well." (PMID 35790919, 2022). "Elevated plasma levels of cytokines i.e. IL-1β, IL-6 and tumor necrosis factor-α (TNF-α) strongly predicts the high mortality associated with acute lung injury." (PMID 33239093, 2020). "TNF-α and IL-6 are the important proinflammatory mediators, which are associated with systemic inflammatory response syndrome, acute lung injury, and mortality." (PMID 32082076, 2019). "TNF-α is implicated in the development of pro-inflammatory processes and neuropathic pain after nerve injury." (PMID 30053799, 2018). "Moreover, the increased secretion of TNF-α and IL-6 from microglia mimics the events happening in traumatic brain injury and metabolic disorders, which in turn increases the risk of neurodegeneration." (PMID 40760135, 2025). "Su’s study demonstrated that Yinchen and a Gancao Decoction significantly reduced the expression levels of IL-1β, IL-6, and TNF-α in the hepatocyte and revealed that hepatocyte necrosis caused by cholestatic liver injury can be alleviated by reducing the release of inflammatory cytokines." (PMID 41471340, 2025). "Indeed, cytokines such as TNF-α-, NO, interleukin 1beta, IL-6, and IL-10 levels are increased in response to acute liver injury caused by free radical production." (PMID 35684137, 2022). "For example, the TLR4 rs10116253-2242C allele enhances the transcriptional activities and expression of TLR4, and trauma patients with the variant C allele have a greater capacity to produce the pro-inflammatory cytokines TNF-α and IL-6 than those with other alleles." (PMID 30683156, 2019). "Activated M1 phenotype microglia produce proinflammatory cytokines such as TNF-α, IL-1β, and IL-6; M2 phenotype microglia produce brain-derived neurotrophic factor and IL-10, which has been associated with neuroprotection after brain injury." (PMID 28529954, 2017). "Moreover, TNF-induced hepatocyte death was augmented by a mutation of alternative p38, suggesting that alternative p38 signaling in hepatocytes contributed more significantly to the pathology of acute liver injury." (PMID 31780731, 2019). "However, excessive training with insufficient recovery causes musculoskeletal trauma with increased production of pro-inflammatory cytokines such as IL-1β, IL-6, and TNF-α, which contributes to symptoms related to performance decrement and exercise-induced fatigue." (PMID 31616260, 2019). "Other studies have also shown that paeoniflorin could protect mice against Bacillus Calmette-Guerin or lipopolysaccharide-induced liver injury, which might be associated with the effects of inhibition of IL-1β and TNF-α release and the promotion of IL-10 production." (PMID 27525026, 2016). "In this study, treatment with CAG decreased the levels of TNF-α, IL-6, and IL-1β, suppressing inflammatory response and alleviating alcohol-induced liver injury." (PMID 40822494, 2025). "Studies have shown that excessive TNF-α signalling can lead to the progression of myocardial fibrosis and heart failure, making it a potential therapeutic target in trauma-related cardiac dysfunction." (PMID 40710793, 2025).
injury (continued). "A further study found that administration of TNF in a generalised model of brain injury had a reduction in SD amplitude, possibly suggesting that TNF, particularly via its receptor TNFR2, has a neuroprotective effect to limit SD during injured states." (PMID 40634990, 2025). "■Decreased COX-2 and CXCL-8 gene expression in human bronchial epithelial cells;■Reduced IL-6 and TNF-α pulmonary levels in a rat model of LPS-induced acute lung injury." (PMID 40298549, 2025). "In cases of acute lung injury, proinflammatory cytokines such as IL-6 and TNF-α stimulate the phosphorylation of VE-cadherin." (PMID 40431442, 2025). "Pro-inflammatory cytokines, including TNF-α and IL-1β, are key mediators of neuropathic pain and contribute to central sensitization following nerve injury." (PMID 40806499, 2025). "Silencing of MNK2 leads to diminished histopathological alterations in the lungs, evidenced by lower neutrophil levels and reduced IL-6 and TNF-α production in cases of acute lung injury." (PMID 39884255, 2025). "All these findings suggest that young plasma can attenuate age-related liver injury by modulating TNF-α and VEGFR2 expression levels." (PMID 40418410, 2025). "D-gal induction led to upregulated mRNA expression of pro-inflammatory cytokines (IL-6, IL-1β, and TNF-α), which are core drivers of the inflammatory cascade in persistent liver injury." (PMID 41614837, 2025). "Among the earliest molecular mediators released after cerebral trauma are the pro-inflammatory cytokines tumor necrosis factor-α (TNF-α) and interleukin-6 (IL-6)." (PMID 41463131, 2025). "Increased expression levels of inflammatory cytokines, such as TNF-α and IL-1β, have been reported in cisplatin-induced kidney injury in mice." (PMID 38890434, 2024). "TNF-α and IL-1β are important in mediating nerve injury-induced glial activation and enhancing synaptic transmission." (PMID 37639183, 2024). "It has been reported that HMGB1 is positively associated with changes in LOX-1, IL-1β, and TNF-α in murine models of COPD and acute lung injury." (PMID 38655086, 2024). "LPS-induced acute liver injury occurs due to inflammatory mediators such as TNF-α, IL-1β, and ROS, affecting mitochondrial function and hepatocyte apoptosis, affecting Kupffer cells and hepatocytes." (PMID 39101083, 2024). "Previous studies have shown that Tau reduces the secretion of pro-inflammatory cytokines, such as TNF-α, NF-κB, and IL-1β, in bleomycin-, endotoxin-, and cigarette smoke- induced acute lung injury." (PMID 39457890, 2024). "Eugenol (10.7 mg/kg) reduced TNFα and IL-6 plasma levels 48 h after the initiation of thioacetamide-induced liver injury in rats." (PMID 38256335, 2023). "Autophagy inhibits TNF toxicity by blocking caspase 8 activation and mitochondrial death pathways in vivo, suggesting that autophagy is a potential therapeutic target in the treatment of TNF-α-induced liver injury." (PMID 38129372, 2023). "A more recent study has also revealed that aurantiamide acetate significantly suppressed TNF-alpha production in LPS-induced acute lung injury in mice." (PMID 37582694, 2023). "An integrative review of 37 studies identified an elevation of IL-6, IL-1β, IL-8 and TNF-α during the first 3 weeks of life as potential, independent predictors of brain injury and neurodevelopmental impairment." (PMID 37049507, 2023). "Concurrently, ASD also downregulated the expression levels of MCP-1, TNF-α and IL-6 proteins in mice model of CCl4-induced liver injury, dose-dependently." (PMID 38223644, 2023). "Soluble factors from L. reuteri significantly reduced the production of proinflammatory cytokines (i.e., IL-6 and TNF-α) by lipopolysaccharide-stimulated macrophages and alleviated lipopolysaccharide-induced acute lung injury in mice." (PMID 37517995, 2023).
injury (continued). "These pathways have been identified as key regulators for the release of various inflammatory mediators, such as tumor necrosis factor alpha (TNF-α) and interleukin-6 (IL-6), which play a vital role in the pathogenesis of acute lung injury." (PMID 37637154, 2023). "A study demonstrated that TMZ improves neuroinflammatory cytokines such as TNF-α and NF-κB p65 in folic acid-induced acute ovarian injury in mice." (PMID 37886007, 2023). "Studies have shown that cisplatin induces a cascade of inflammatory reactions with increased production of proinflammatory cytokines, particularly TNF-α, which has a central role in mediating cisplatin-induced inflammatory renal injury." (PMID 36814499, 2023). "For example, let-7a-5p and let-7c-5p overexpression has suppressed TNFα expression, while let-7c-5p improved neurological outcomes in a murine model of traumatic brain injury by suppressing neuroinflammation." (PMID 36992332, 2023). "The results demonstrated that both BE and TQ attenuated ConA-induced acute liver injury mainly via suppressing the TNF-α and IFN-γ's production and blocking the NF-κB signaling." (PMID 35958317, 2022). "They found that the expression levels of p38 MAPK, NF-κB p65, IL-1β, and TNF-α protein in rats with kidney injury were significantly higher than those in the control group." (PMID 36296715, 2022). "Pretreatment with Bacillus species spores (B. licheniformis, B. indicus, B. subtilis, B. clausii, and B. coagulans) lowered the serum levels of pro-inflammatory cytokines (TNF-α and IL-1β) against acetaminophen-induced acute liver injury in rats." (PMID 35799262, 2022). "It has been shown that inflammatory chemokines, particularly interleukin-6 (IL-6) and tumor necrosis factor-α (TNF-α), play an important role in the onset of acute lung injury." (PMID 36532788, 2022). "A recent study in China shows that GL reduces the expression level of HIF-1α, inhibits the release of inflammatory cytokines IL-6 and TNF-α, and plays protective roles in acute lung injury." (PMID 35967372, 2022). "In a study from the DILIN study group in the US, six patients with TNF-alpha inhibitors induced liver injury and additional 28 patients from the literature were analyzed: infliximab (n = 26), etanercept (n = 4) and adalimumab (n = 4)." (PMID 35222034, 2022). "Western blotting revealed that paeonol also inhibited the total expression of HMGB1, NF-κB P65 and TNF-α in the lung tissue of acute lung injury rats." (PMID 36501418, 2022). "Macrophages are one of the cellular sources of proinflammatory cytokines, including TNF-α, and exacerbate cisplatin-induced kidney injury." (PMID 36498769, 2022). "A patient-reported history of recent head trauma was present in 30/51 (61%) patients, and only IL-1α (p = 0.025) and TNF-α (p = 0.026) showed significantly higher inflammatory mediator concentrations in these patients." (PMID 36158966, 2022). "Inhibiting p65 activation, that is, inhibiting the production of p-p65, can reduce LPS-induced acute lung injury and reduce the production of TNF." (PMID 35548340, 2022). "Pro-inflammatory cytokines such as interleukin-1β and tumor necrosis factor-α are significantly elevated in patients with acute lung injury/acute respiratory distress syndrome." (PMID 35469161, 2022). "In a study of myocardial ischemia-reperfusion injury, researchers found that Puerarin can reduce the expression of inflammatory cytokines IL-6, IL-1β, and TNF-α through AMPK/Akt/GSK-3β /Nrf2 signaling pathway to prevent myocardial ischemia-reperfusion injury." (PMID 35482440, 2022). "Expressions of TNF-α, IL-1β, IL-6, and IL-8 cytokines in rats with acute lung injury induced by oleic acid were downregulated in the TCZ and DEX groups compared to the OA group (P < 0.05)." (PMID 36115998, 2022).